PDX1 (pancreatic and duodenal homeobox 1)
Diseases named in the same sentence as PDX1 in open-access papers (continued):
Sharing a sentence is not in itself a finding about the gene and the disease.
adenovirus infection (1 paper, 2011). "Twenty five percent of cells were capable of activating the ectopic pancreatic insulin promoter upon PDX-1 infection; no signal was detected with control adenovirus infection." (PMID 22028850, 2011).
anal squamous cell carcinoma (1 paper, 2021). A squamous cell carcinoma (SCC) arising from the anal canal or the anal margin (perianal skin). "This study identified and characterized the Kras-driven, female sex hormone-dependent development of anal squamous cell carcinoma (SCC) in the LSL-KrasG12D; Pdx1-Cre (KC) mouse model that is not dependent on papillomavirus infection." (PMID 34735515, 2021).
anal tumor (1 paper, 2021). "At nine months, expression of Pdx1 in KC female anus / anal tumor was significantly higher than KC male anus." (PMID 34735515, 2021). "Furthermore, the evidence presented disputes the possibility that sex-bias differences in anal tumor formation was simply due to the absence of Pdx1, Cre or activated KrasG12D expression in male anal tissue." (PMID 34735515, 2021).
cognitive decline (1 paper, 2016). "In summary, the present study demonstrated that Pdx1+/−/APP/PS1 mice exhibit enhanced cognitive decline, Aβ plaque deposition, tau hyperphosphorylation, the loss of synaptic spine protein, and activation of microglia and astrocytes." (PMID 27406855, 2016).
colitis (1 paper, 2016). Inflammation of the colon. "Thirty-seven (37 = 58.7%) of these DMRs associated with genes, but only 6 (16.2%) of those have been implicated in either colitis (PTPRF, ELTD1, and GDNF) or CRC (PTPRF, ELTD1, PDX1, CCK, and AGPAT1)." (PMID 27006956, 2016).
COVID-19 (1 paper, 2022). A disease caused by infection with severe acute respiratory syndrome coronavirus 2. "In summary, the expression patterns of CD36, GLUT2, IRS1, IRS2, PDX1, and PPARG in the pancreas were altered upon SARS-CoV-2 infection, implying that islet function may be compromised in patients with COVID-19." (PMID 35343389, 2022). "In the COVID-19 patient without SARS-CoV-2 virus expression in the pancreas (SARS-CoV-2 negative), CD36, GLUT2, IRS2, and PDX1 were widely distributed in the pancreatic, serous acini, duct (exocrine gland) and islet (endocrine gland)." (PMID 35343389, 2022).
Donohue syndrome (1 paper, 2023). Leprechaunism is a congenital form of extreme insulin resistance (a group of syndromes that also includes Rabson-Mensenhall syndrome, type A insulin-resistance syndrome, and acquired type B insulin-resistance syndrome) characterized by intrauterine and mainly postnatal severe growth retardation. "Whereas autoimmune monogenic diabetes, Donohue syndrome and Wolcott–Rallison syndrome are known to have a poor prognosis, death in infancy/childhood in patients with PDX1 and ABCC8 pathogenic variants is rare." (PMID 36398453, 2023).
duodenal adenocarcinoma (1 paper, 2023). A carcinoma that arises from glandular epithelial cells of the duodenum. "The Pdx1 protein was widely expressed in gastric epithelial and intestinal mucosae such that Pdx1-cre/T antigen mice also suffered from gastric adenoma and duodenal adenocarcinoma." (PMID 37247123, 2023).
dwarfism (1 paper, 2010). "These Pdx1-Cre, KrasG12D/+, p21+/− (KCp21) mice were also affected by a dwarfism phenotype." (PMID 20452353, 2010).
epidermal cysts (1 paper, 2010). "Pdx1-Cre;Kras;N1ko mice developed the following skin pathologies: squamous papillomas involving the ear, neck, lips, anal and vulvo-vaginal skin, epidermal cysts, and sebaceous gland hyperplasia and cutaneous horns to lesser extend." (PMID 21042537, 2010).
Fulminant hepatitis (1 paper, 2021). Acute hepatitis complicated by acute liver failure with hepatic encephalopathy occurring less than 8 weeks after the onset of jaundice. "This overexpression of Pdx1 repressed the hepatic phenotype causing fulminant hepatitis and hepatic agenesis." (PMID 33666218, 2021). "Pdx1 expression however was found to drive fulminant hepatitis, possibly as a result of the broad and sustained expression of Pdx1 throughout the liver." (PMID 33666218, 2021).
gallbladder cancer (1 paper, 2017). "Thus, forced expression or inactivation of genes in the gallbladder using Pdx1-Cre can be a new approach in developing mouse models for gallbladder cancer." (PMID 29142904, 2017).
gallbladder tumor (1 paper, 2017). "We determined Cre recombination activity of Pdx1-Cre in the gallbladder using a reporter strain and examined gallbladder tumor development in the KrasLSL- G12D/+;Pdx1-Cre mice." (PMID 29142904, 2017).
gastric diseases (1 paper, 2022). "In the context of gastric diseases, Krishnamurthy and collaborators studied gastric organoids derived from two individuals with homozygous mutations in PDX1 (pancreatic and duodenal homeobox 1), causing a loss of its expression." (PMID 36360266, 2022).
Gastric Metaplasia (1 paper, 2025). Intestinal metaplasia of the gastric mucosa is an intermediate precancerous gastric lesion in the gastric cancer cascade from chronic gastritis and atrophy to dysplasia and adenocarcinoma. "PDX1 expression in gastric metaplasia is significant as this transcription factor is normally restricted to pancreatic and duodenal tissues, and its ectopic expression in human gastric intestinal metaplasia indicates aberrant developmental programming." (PMID 40673273, 2025). "The expression of PDX1 in gastric metaplasia is particularly significant as this pancreatic transcription factor is ectopically expressed in human gastric intestinal metaplasia and may drive transdifferentiation toward an intestinal phenotype." (PMID 40673273, 2025).
giant cell tumor of bone (1 paper, 2013). "The downregulation expression of Pdx1 was closely related to the balance between oncogene and antioncogene destroyed and the invasiveness of giant cell tumor of bone (GCTB)." (PMID 24455688, 2013).
glucose metabolic disorders (1 paper, 2025). "Based on the role of PDX1 in glucose regulation, PDX1 may be implicated in glucose metabolic disorders during pregnancy." (PMID 40405977, 2025).
Hepatitis (1 paper, 2017). Inflammation of the liver. "Despite the early success with Pdx-1, some studies have shown that Pdx-1 induced exocrine transdifferentiation, resulting in the development of hepatitis and an increased likelihood of autoimmune destruction." (PMID 28279194, 2017).
Hypertension (1 paper, 2015). The presence of chronic increased pressure in the systemic arterial system. "We have previously demonstrated that rs146021107 of PDX1 is significantly associated with myocardial infarction, although, to the best of our knowledge, the association of PDX1 polymorphisms with hypertension has not yet been reported." (PMID 25813534, 2015).
intestinal tumor (1 paper, 2025). "Beyond its role in K-cell differentiation, PDX1 enhances Gip expression via binding to the Gip promoter, as demonstrated by enhanced Gip reporter activity in mouse intestinal tumor STC-1 cells transfected to overexpress Pdx1." (PMID 40024571, 2025).
leukemia (1 paper, 2019). A malignant (clonal) hematologic disorder, involving hematopoietic stem cells and characterized by the presence of primitive or atypical myeloid or lymphoid cells in the bone marrow and the blood. "Interestingly, the most sensitive leukemia with the lowest EC50 value (PDX1) showed the highest BCL-2 protein expression." (PMID 31358732, 2019).
lipid metabolism disorders (1 paper, 2023). "Meanwhile, Pdx-1 may also be a key factor related to the adverse effects of lipid metabolism disorders on pancreatic islets." (PMID 36901708, 2023).
lung adenocarcinoma (1 paper, 2022). A carcinoma that arises from the lung and is characterized by the presence of malignant glandular epithelial cells. "In our study, PDX1 tends to play a carcinogenic role, which may be due to the transformation of lung adenocarcinoma." (PMID 36400857, 2022).
macrosomia (1 paper, 2025). "The adjusted analysis showed that elevated PDX1 levels in early pregnancy were associated with reduced risks of GDM (aOR 0.287, 95%CI 0.130-0.636, P=0.002), macrosomia (aOR 0.249, 95%CI 0.076-0.811, P=0.021) and composite adverse pregnancy outcomes (aOR 0.496, 95%CI 0.256-0.960, P=0.037)." (PMID 40405977, 2025).
metastasis (1 paper, 2020). The spread or migration of cancer cells from one part of the body (where they first appeared) to another. "Interestingly, in patient 2, both the primary and the corresponding liver metastasis only had few PDX1-positive cells (potential insulin producing cells), so perhaps the solitary liver metastasis (3 cm) did not grow to a size in which a low percentage of cells could have caused symptoms." (PMID 32103422, 2020).
Mitchell-Riley syndrome (1 paper, 2024). "The phenotypic spectrum observed in our patients with PDX1-NDM overlaps with features seen in Mitchell-Riley syndrome caused by recessive RFX6 variants (OMIM:615710)." (PMID 39542526, 2024).
mucinous adenocarcinoma (1 paper, 2018). An invasive adenocarcinoma composed of malignant glandular cells which contain intracytoplasmic mucin. "HNF4α and PDX1 are transcription factors that regulate gastrointestinal differentiation and are expressed in human invasive mucinous adenocarcinoma and mouse models of this disease." (PMID 30475207, 2018).
neuroendocrine carcinoma (1 paper, 2024). A malignant neuroendocrine neoplasm composed of cells containing secretory granules that stain positive for NSE and chromogranin. "Antibody array protein chip analysis of transcription factors in 3DiNET ORION cells revealed expression of several intracellular transcription factors involved in neuroendocrine cancer pathobiology—Snail, GATA4, FoxA2, Sox-2, PDX-1 and E-cadherin." (PMID 39103560, 2024). "Protein array analysis showed expression of multiple intracellular transcription factors involved in neuroendocrine cancer pathobiology—Snail, GATA4, FoxA2, Sox-2, PDX-1 and surface molecule (E-cadherin)." (PMID 39103560, 2024).
oral cancer (1 paper, 2021). "According to our data, the expression level of the ITGB6 gene, whose overexpression is known to facilitate EMT and is associated with the invasiveness of oral cancer cells, decreases in cells expressing PDX1." (PMID 34503200, 2021).
oral squamous cell carcinoma (1 paper, 2021). "In Colo357 cells expressing PDX1, there is an increase in MMP3 gene expression, and high expression levels in oral squamous cell carcinoma cells are associated with metastasis and poor prognosis for patients." (PMID 34503200, 2021).
osteosarcoma (1 paper, 2022). A usually aggressive malignant bone-forming mesenchymal neoplasm, predominantly affecting adolescents and young adults.
overnutrition (1 paper, 2019). An imbalanced nutritional status resulting from excessive intake of nutrients. "Despite an early increase in β cell mass induced by early overnutrition, the β cell dysfunction reflected in the reduced islet insulin content and reduced Pdx1 expression eventually leads to β cell death." (PMID 30842440, 2019). "The reduced Pdx1 expression that was observed in young early overnutrition males and the later development of low islet insulin content, suggests a primary β cell dysfunction induced by early overnutrition." (PMID 30842440, 2019).
papillary thyroid cancer (1 paper, 2024). "Similarly, the translational regulation of pancreatic and duodenal homeobox 1 (PDX1) in pancreatic β cells and ERBB2 in radioiodine-refractory papillary thyroid cancer also relies on IGF2BP2’s recognition of m6A methylation." (PMID 39596216, 2024).
Rectal prolapse (1 paper, 2018). Protrusion of the rectal mucous membrane through the anus. "One previous study did mention rectal prolapse in passing as a reason for censorship in survival analysis of Pdx1-Cre;LSL-KrasG12D/+;Trp53LSL-R172H/wt mice." (PMID 29596465, 2018).
skin tumor (1 paper, 2010). "However, double Notch1 and Notch2 knockout mice (Pdx1-Cre;Kras;N1ko;N2ko) featured an accelerated skin tumor formation suggesting an essential role of Notch1 ablation in epidermal lesion development and a promoting role of Notch2 deletion." (PMID 21042537, 2010). "In our study, Pdx1-Cre;Kras;N1ko but not Pdx1-Cre;Kras;N2ko or Pdx1-Cre;Kras developed skin lesions which points to the importance of Notch1 but not Notch2 for skin tumor development." (PMID 21042537, 2010).
teratocarcinoma (1 paper, 2022). A germ cell tumor characterized by the presence of an embryonal carcinoma component and a teratoma component. "ChIP analyses proposed a RARE (retinoic acid response element) located upstream of the transcription start site of Pdx1 in teratocarcinoma cells (F9)." (PMID 36101450, 2022).
tumor (221 papers, 2009 to 2026). "Using a genetic approach to assess E-cadherin/Cdh1 function in the aberrant Snail expression model, we knocked out one floxed allele of the Cdh1 tumour suppressor in Pdx1-Cre;KrasG12D/+;SnailKI/+ mice." (PMID 36882420, 2023). "The role of PDX-1 changes from tumor suppressive to oncogenic, with cells losing PDX-1 expression while undergoing EMT and PDX-1 loss being associated with poor patient outcomes." (PMID 35892853, 2022). "In contrast, its loss decreases cell survival and tumor growth in vivo, suggesting that PDX1 acts as an oncogene." (PMID 34888306, 2021). "Based on previous studies showing PDAC development in mice harboring both Kras mutation and loss of tumor suppressor activity, we examined Pdx1-Cre; KL−/−; KrasG12D/+ mouse pancreata for lesions." (PMID 34944918, 2021). "In this study, we found that Pdx1 expression and consequent Cre-recombinase expression in the anal epithelium caused activation of the KrasG12D gene in the anal epithelium and tumor development." (PMID 34735515, 2021). "The phenotype of Pdx1-Cre; KL−/−;KrasG12D/+ mice is less pronounced, compared to models combining loss of other tumor suppressors with Kras mutations." (PMID 34944918, 2021). "PDX1 presented hypermethylation and lower expression in tumours with mutations in the ATRX/DAXX/MEN1 genes (T2 and T3) than in wild-type tumours (T1)." (PMID 33536587, 2021). "In line with CTCDOs enhanced aggressiveness and tumor-forming capacity, we found an increased expression of several factors implicated in stemness maintenance both in normal and malignant tissues such as PDX1, Goosecoid, Oct3/4, SOX2, DLL1, Cited-2." (PMID 35260172, 2022). "EFNA1 could also interact with ephrin receptor EPHA1, which is overexpressed in PTC and then associates with tumor growth, invasiveness, and metastasis, to trigger transcription factor PDX1, which is modified by phosphorylation to cause its activation." (PMID 31126066, 2019). "Third, cancer-associated stroma may restrain circulating antibody to target tumor site in Pdx1-cre; LSL-KrasG12D mice because cancer-associated stromal cells have been reported to cause lower FDG uptake in higher vascular perfusion." (PMID 28874965, 2016). "Overall, our findings suggest that PDX1 plays a tumor-promoting role in human PCa cells by influencing expression of metabolites in insulin, inflammatory, and epithelial-mesenchymal transition (EMT) signaling pathways." (PMID 41955005, 2026). "It has been suggested that lack of EZH2 would lead to failed transcriptional silencing of CDK-Inhibitor 2A (p16) in the PDX1- positive metaplastic lesions, accelerating Kras-driven neoplasia." (PMID 40135141, 2024). "Further, we evaluated the efficacy of L_GEM and ONC201 in PC cells and “KrasLSL-G12D; p53LoxP; Pdx1-CreER (KPC) triple mutant xenograft tumor-bearing mice." (PMID 38553450, 2024). "Overall, the tumor cellular complexity of the source biopsies was maintained for an extended period in mice until experimental endpoint, 106 d and 161 d for PDX1 and PDX2, respectively." (PMID 39386738, 2024). "The results depicted demonstrate that the combination of SIRPα-Fc and VEGFR1-Fc resulted in the complete suppression of tumor growth in the Hu-PDX1 model." (PMID 38532108, 2024).